JAK2 (Janus kinase 2)
Diseases named in the same sentence as JAK2 in open-access papers (continued):
Sharing a sentence is not in itself a finding about the gene and the disease.
Arterial thrombosis (18 papers, 2018 to 2026). The formation of a blood clot inside an artery. "The arterial thrombosis associated with ET primarily stems from platelet hyperreactivity, leukocyte-platelet aggregation, and endothelial dysfunction-all driven by JAK2 gene mutations." (PMID 41560006, 2026). "Recently, JAK2 mutations and cardiovascular risk factors are listed as the new risk factors for arterial thrombosis due to their prognostic value." (PMID 36611455, 2023). "All cases of arterial thrombosis (four patients; 15.4 %) were JAK2 V617F mutated ET whereas all hemorrhagic complications (two patients; 7.7%) occurred in cases of CML." (PMID 31350969, 2019). "In this regard, aspirin therapy is very important for JAK2-mutated patients, because of their increased risk for arterial thrombosis." (PMID 29321520, 2018). "Multivariate analysis confirmed older age (for age ≥60 years; HR 2; p < 0.001) and the presence of JAK2 mutation (HR 1.4; p = 0.02) as independent risk factors for future arterial thrombosis, whereas the protective effect of cytoreduction was confirmed (HR 0.4; p = 0.04)." (PMID 38238287, 2024). "Univariate analysis for arterial thrombosis-free survival (A-TFS) identified older age (p < 0.001), male sex (p = 0.03), presence of JAK2 mutation (p = 0.04), cardiovascular risk factor (p = 0.002) and previous arterial event (p = 0.006) as risk factors for arterial thrombosis during follow-up." (PMID 38238287, 2024). "The presence of JAK2 V617F mutation is associated with higher risk of arterial thrombosis." (PMID 30564475, 2018). "While arterial thrombosis is a recognized complication of ET, CALR-mutated ET is typically associated with a lower thrombotic risk compared to JAK2-mutated disease." (PMID 40278216, 2025). "In agreement with prior studies, JAK2 mutation, prior CVD, and early post-MPN diagnosis have been associated with increased risks of arterial thrombosis in MPNs in prior studies." (PMID 37367089, 2023). "Other coagulation complications, such as arterial thrombosis (14% vs. 9%; p = 0.3) and haemorrhage (9% vs. 5%; p = 0.3), were not significantly different in patients with ET with JAK2 mutations than those with CALR mutations." (PMID 36611455, 2023). "A study was also conducted in patients with arterial thrombosis for JAK2 V617F mutation and no mutation was found in any of the patients." (PMID 36611455, 2023). "Additionally, MPN patients with JAK2 mutations have an increased risk of arterial thrombosis compared with patients without JAK2 mutations." (PMID 37367089, 2023). "Patients with PV with the JAK2 V617F allele burden of >75% exhibited higher thrombotic risk than those with <25% (p = 0.03) and higher risk of venous thromboembolism (VTE) when their JAK2 allele burden is >20%, but not for arterial thrombosis." (PMID 36611455, 2023).
Cognitive impairment (18 papers, 2015 to 2026). Abnormal cognition is characterized by deficits in thinking, reasoning, or remembering. "The activation of JAK2/STAT3 may be useful in treating cognitive impairment associated with aging‐related disorders." (PMID 34262731, 2021). "We found that the positive effect of exercise on cognitive impairment is reversed after activating JAK2." (PMID 35578689, 2022). "Overexpression of neuritin ameliorated cognitive impairment, and the JAK2 inhibitor showed the same effects in diabetic mice." (PMID 33729996, 2021). "We observed that the CCH process-induced cognitive impairment decreased CNTF/CNTFRα/JAK2/STAT3 signaling, and induced irreversible neuronal death in the hippocampus." (PMID 33519417, 2020). "Based on these data, we speculated that the JAK2/STAT3 pathway is involved in regulating cognitive impairment induced by T2DM; it is unclear whether exercise plays a role in regulating the JAK2/STAT3 pathway." (PMID 35578689, 2022). "STAT3 activation is dependent on the JAK2/STAT3 signaling pathway, and the activation of JAK2/STAT3 may be useful in treating cognitive impairment associated with aging‐related disorders." (PMID 34262731, 2021). "Therefore, in the present study, we explored the effect of aerobic exercise on cognitive impairment in T2DM mice and investigated whether the JAK2/STAT3 and AMPK/SIRT1 pathways are involved in the underlying mechanism." (PMID 35578689, 2022). "In this study, cognitive function was significantly impaired in the T2DM mice; aerobic exercise improved cognitive impairment through activating the AMPK/SIRT1 signalling pathway and inhibiting the JAK2/STAT3 signalling pathway in T2DM mice." (PMID 35578689, 2022). "Here, we describe an unusual case of a 40-year-old woman with rapidly progressive cognitive impairment and limb weakness, diagnosed with CVT accompanied by JAK2 V617F-positive PMF." (PMID 32846801, 2020). "Recent data also suggest that inactivation of the JAK2/STAT3 signaling axis and M1 mAChR downregulation play a critical role in cognitive impairment observed in KLOTHO mutant mice." (PMID 25961830, 2015). "The SZRD, especially the L-SZRD, may improve the cognitive impairment and ameliorate the neural degeneration in APP/PS1 transgenic mice through inhibiting Aβ accumulation and neuroinflammation via the JAK2/STAT3 pathway." (PMID 33478552, 2021). "Furthermore, treatment with SLT decreases LCN2 expression and the phosphorylation levels of Janus kinase-2 (JAK2) and signal transducer and activator of transcription-3 (STAT3) and mitigates the cognitive deficits in VaD rats." (PMID 33532143, 2021). "Thus, knockout of BDNF or TrkB in the hippocampus results in JAK2/STAT3, C/EBPβ, and δ-secretase upregulation and activation, resulting in increased neuroinflammation and neuronal cell death, leading to cognitive impairments." (PMID 31315045, 2019).
fibrosis (17 papers, 2017 to 2026). the formation of excess fibrous connective tissue in an organ or tissue in a reparative or reactive process. "This study contributes to the existing literature by identifying THBS1 and the JAK2/STAT3 pathway as promising molecular targets for therapeutic intervention in RILI-associated fibrosis, offering a feasible mechanistic basis for future antifibrotic strategies." (PMID 41394148, 2025). "There is a possible link between JAK2, a pivotal upstream regulator of the JAK pathway, and tubulointerstitial fibrosis, which was suggested by the temporal association of upregulated JAK2 level and evolution of human DKD." (PMID 34327204, 2021). "Our group described that JAK2 is overexpressed in a BLM-induced fibrosis rat model, as well as its phosphorylated form." (PMID 34207510, 2021). "To ascertain whether PatA impacts HG-induced inflammatory fibrosis via the JAK2/STAT3 pathway, we performed Western blot analysis." (PMID 38794201, 2024). "Furthermore, loganin can achieve cardioprotective effects through attenuating cardiac fibrosis, decreasing pro-inflammatory cytokine secretion, and suppressing the phosphorylation of critical proteins such as JAK2, STAT3, p65, and IκBα." (PMID 34194329, 2021). "While the direct contribution of STAT in autophagy in ILDs has not been described, our group found that pharmacological inhibition of JAK2/STAT3 increased autophagy in the lungs of BLM-induced fibrosis in rats, which evidences a possible role for this pathway in autophagy in ILDs." (PMID 34207510, 2021).
Hyperglycemia (17 papers, 2013 to 2025). An increased concentration of glucose in the blood. "Our findings revealed that poststroke hyperglycemia, glucose intolerance, and brain injury were linked to high IL-6 content, and the Jak2 inhibitor AG490 reversed these alterations." (PMID 34943061, 2021). "The JAK1/JAK2 inhibitor LN3103801 prevents/reverses hyperglycemia by dual blockade of IFN-γ-mediated MHC-I overexpression in beta-cells and γc cytokine-driven T-cell activation, without compromising antitumor efficacy in NOD mice." (PMID 40534861, 2025). "Recently, numerous studies have implicated the JAK2/STAT3 signaling pathway in the progression of DN and various diabetic characters such as hyperglycemia, angiotensin II, and AGEs can also activate the JAK/STAT pathway." (PMID 34784849, 2021). "In conclusion, PCr improves mitochondrial functions and exerts an antiapoptotic effect in vivo and in vitro exposed to oxidative stress by hyperglycemia through the JAK2/STAT3 signaling pathway." (PMID 31885809, 2019). "In the current study, increased levels of both long and short forms of leptin receptor, as well as, increased levels of GRB2, phospho-STAT3, and phospho-JAK2 were observed under hyperglycemia." (PMID 24260287, 2013). "Moreover, active JAK2 and leptin receptor were almost completely colocalized under hyperglycemia providing strong evidence that leptin receptor signaling is directly induced by high glucose levels in mammary epithelial cells." (PMID 24260287, 2013). "Mice preconditioned with REM have been reported to display a much lower risk of myocardial injury following I/R procedures, whereas hyperglycemia-induced oxidative stress could diminish REM cardioprotection by damaging the Caveolin-3-regulated PI3K/Akt and JAK2/Stat3 signaling pathways." (PMID 34612779, 2021). "Studies have shown the ability of NTS to enhance growth hormone signaling via the JAK2/STAT5b/IGF-1 axis and to produce anti-inflammatory effects against hyperglycemia in human monocytes." (PMID 34068523, 2021). "Inhibition of JAK2 and HIF1A expression can partially attenuate hyperglycaemia-elicited oxidative stress." (PMID 34956587, 2021). "Importantly, Jak2 deficiency in myeloid cells prevented HFD-induced hyperinsulinemia and hyperglycemia and improved both insulin and glucose tolerance as compared with that of HFD-fed Jak2+/+ mice." (PMID 40801626, 2025). "Thus, hyperglycemia-induced oxidative stress abrogates RPC cardioprotection by impairing Cav-3-modulated PI3K/Akt and JAK2/STAT3 signaling." (PMID 31583053, 2019). "Leptin receptor signaling classically utilizes the JAK2/STAT3 signaling pathway; therefore, we assessed the levels of JAK2 and STAT3 activation under high glucose conditions and found that hyperglycemia resulted in increased JAK2 phosphorylation in all cell lines within 72 hr." (PMID 24260287, 2013). "It activates the JAK2/STAT pathway and promotes glucose uptake by increasing GLUT4 translocation in different signaling pathways in skeletal muscle cells at a low concentration range, thereby providing beneficial functions for preventing hyperglycemia and maintaining glucose homeostasis." (PMID 40699692, 2025). "Therefore, in contradiction with the results of the in vitro experiments, the in vivo experiments confirmed that hyperglycemia did not affect the expression of p-JAK2, p-STAT3, CAV-1, and p-NR2B." (PMID 30830585, 2019).
nasopharyngeal carcinoma (17 papers, 2014 to 2025). A carcinoma arising from the nasopharyngeal epithelium. "Apart from that, RIG-I was reported to regulate the resistance of nasopharyngeal carcinoma to paclitaxel by regulating IFN/JAK2." (PMID 35587143, 2022). "Previous work has identified the JAK2/STAT3 pathway to be involved in cisplatin resistance of nasopharyngeal carcinoma and epirubicin resistance of NSCLCs." (PMID 34612768, 2021). "For example, activation of Janus kinase 2 (JAK2)/STAT3 pathway has been shown to suppress miRNA-1 expression by inhibiting miRNA-1 promoter activity in nasopharyngeal carcinoma." (PMID 31157242, 2019). "RIG‐I promotes IFN/JAK2 and ER stress response‐mediated apoptosis to inhibit chemoradiation resistance in nasopharyngeal carcinoma." (PMID 31464090, 2019). "Previous research revealed that OIP5 could promote metastasis of nasopharyngeal carcinoma cells by promoting EMT via modulation of JAK2/STAT3 signal." (PMID 35242130, 2022). "The aim of the study was to investigate the effect associated with the protein expression of VEGF, JAK2 and STAT3 on the clinicopathologic characteristics and prognosis in the development and progression of nasopharyngeal carcinoma (NPC)." (PMID 30123088, 2018). "AGK was also considered to be a promoter of resistance to paclitaxel in nasopharyngeal carcinomas and this chemoresistance properties which eventually mediate tumor growth and metastasis is facilitated by overexpressed FOXM1 via JAK2/STAT3 signaling pathway." (PMID 40176914, 2025). "This study is intended to explore the correlation of IL-6 and JAK2/STAT3 signaling pathway with clinicopathological features and prognosis in nasopharyngeal carcinoma (NPC)." (PMID 34165442, 2021). "Additionally, OIP5 KD has been observed to inhibit epithelial–mesenchymal transition (EMT) and downregulate phosphorylated JAK2 and phosphorylated STAT3 in the JAK2-STAT3 pathway in nasopharyngeal carcinoma." (PMID 38474305, 2024). "Interestingly, a recent study has shown that gp130 is down-regulated in EBV-positive nasopharyngeal carcinoma primary tumors and determines the lack of activation of the Jak2/Stat pathway following IL-27 release, resulting in an impairment of NK cell function and immune surveillance." (PMID 24731550, 2014).
oral squamous cell carcinoma (17 papers, 2016 to 2025). "For example, CCR7 and its ligand chemokine ligand 21 (CCL21) promote the EMT and up-regulate the stemness of oral squamous cell carcinoma by activating the JAK2/STAT3 signaling pathway." (PMID 35538537, 2022). "P. gingivalis also appears to stimulate IL-6 expression via the janus kinase 2/glycogen synthase kinase 3 beta/signal transducer and activator of transcription 3 (JAK2/GSK3-β/STAT3) signaling pathway, which is linked to carcinogenesis and the development of oral squamous cell carcinoma." (PMID 40806122, 2025). "So we believe that neutrophils may promote tumor progression (proliferation and invasion) via regulating EMT and JAK2/STAT3 signaling through Chemerin in Oral squamous cell carcinoma." (PMID 35155249, 2022). "Additionally, P. gingivalis seems to promote IL-6 expression through the janus kinase 2/glycogen synthase kinase 3 beta/signal transducer and activator of transcription 3 (JAK2/GSK3-β/STAT3) pathway, which is associated with carcinogenesis and oral squamous cell carcinoma." (PMID 40805993, 2025). "IL-6 could promote proliferation via JAK2/STAT3/SOX4 pathway in oral squamous cell carcinoma cells." (PMID 39963655, 2024). "JAK2/STAT3 is a well‐known oncogenic pathway that leads to a variety of solid malignancies, including oral squamous cell carcinoma." (PMID 36708238, 2023). "CCL18/PITPNM3 axis also activates JAK2/STAT3 signaling pathway to promote the growth and metastasis of oral squamous cell carcinoma cells." (PMID 35609322, 2022). "For example, in oral squamous cell carcinoma, the CCL21/CCR7 axis activates the JAK2/STAT3 signaling pathway to regulate the progression of EMT and promote the stemness of oral squamous cell carcinoma." (PMID 33788424, 2021). "A CC chemokine receptor 7 (CCR7) and CCL21 are abundant in oral squamous cell carcinoma (OSCC) tissues, where they regulate EMT process and promote OSCC desiccation through activation of the JAK2/STAT3 signaling pathway." (PMID 34421979, 2021).
portal hypertension (17 papers, 2012 to 2025). Increased blood pressure in the portal venous system. "In the present study, we found up-regulated JAK1 and JAK2 were associated with liver disease in humans and mice, while knockdown of JAK1 and JAK2 inhibited activation, proliferation, and migration of HSCs." (PMID 35382859, 2022). "In experimental models, the administration of a JAK2 inhibitor has been shown to decrease hepatic vascular resistance, thereby alleviating portal hypertension." (PMID 39997697, 2025). "This case describes a middle-aged man who developed BCS secondary to JAK2-positive ET, complicated by AvWS, variceal bleeding, and portal hypertension." (PMID 41589191, 2025). "Despite the typical association of these patients with the V617F mutation of the JAK2 gene, the particular difficulty in diagnosis of ET in this syndrome stands out, since the elevated platelet count characteristic of ET might be concealed by factors such as portal hypertension and hypersplenism." (PMID 40242703, 2025). "With the diagnosis of SBP complicating pre‐hepatic portal hypertension secondary to JAK 2 positive ET, patient was started on cytoreductive therapy (hydroxyurea) under close hematological monitoring." (PMID 37405042, 2023). "Stimulation of the AT1 receptor in HSC induces fibrosis and portal hypertension through Janus kinase 2 (JAK2)." (PMID 32392802, 2020). "Another target of miRNA-192 that showed overlap with known pathways of alcoholic hepatitis is Jak2/Arhgef1 signaling pathway, which is correlated with severity of liver disease." (PMID 26264599, 2015). "This receptor facilitates fibrosis and portal hypertension through Janus kinase 2 (JAK2) in HSCs." (PMID 32392802, 2020). "Renin-induced portal hypertension can be ameliorated either by JAK2 inhibitors or Mas agonists." (PMID 31406138, 2019). "Although STAT3 signaling might be more important than STAT5 in HCC progression and miR-196b could activate STAT3 by targeting SOCS2 in macrophages, previous work showed that importance of JAK2/STAT5 signaling in liver metabolism, liver diseases, and HCC36." (PMID 30988277, 2019). "In conclusion, our finding suggested that salidroside could ameliorate hypoxia‐induced liver oxidative stress and inflammation via Nrf2 and JAK2/STAT3 signaling pathways, which is likely to be a therapeutic candidate for the prevention and treatment of liver disorders at high altitudes." (PMID 34532015, 2021).
renal cell carcinoma (17 papers, 2012 to 2026). "A recent study showed that ISG15 can promote proliferation and metastasis through IL6/JAK2/STAT3 signaling in renal cell carcinoma." (PMID 40874680, 2025). "Studies have shown that IL-6 can significantly increase proliferation and metastasis in cancers, such as renal cell carcinoma (RCC) due to the activation of JAK2/STAT3, a pro-inflammatory pathway." (PMID 39478996, 2024). "In renal cell carcinoma cells, knock-down of IL4Rα or IL13Rα1 induced cell cycle arrest and apoptosis by suppressing JAK2-mediated phosphorylation of FOXO3." (PMID 33419470, 2021). "In renal cell carcinoma cells, knock-down of IL4Rα or IL13Rα1 and pharmacological inhibition of JAK2 induced cell cycle arrest and apoptosis of cancer cells." (PMID 33419470, 2021). "In renal cell carcinoma cells, the silencing of IL4Rα expression reduced interaction between JAK2 and FOXO3 and resulted in stabilizing FOXO3." (PMID 33419470, 2021). "In renal cell carcinoma, miR-135a reduced cell viability by targeting C-Myc and JAK2, thus blocking the JAK2/STAT3 pathway." (PMID 32944391, 2020). "In renal cell carcinoma, IL1R2 promotes tumor progression through the JAK2/STAT3 pathway." (PMID 37728418, 2023).
acute leukemia (16 papers, 2007 to 2025). A clonal (malignant) hematopoietic disorder with an acute onset, affecting the bone marrow and the peripheral blood. "For example, rs2230724, a new SNP of JAK2, was associated with the susceptibility of acute leukemia and its subtypes." (PMID 23717640, 2013). "JAK2 V617F mutation is rare in acute leukemias but occur in 2 of 11(18%) patients with AMKL." (PMID 36267971, 2022). "A similar inhibition of mitochondrial respiration by α-KG was observed in UKE-1, a JAK2-mutant ET transformed acute leukemia cell line." (PMID 38060311, 2024). "JAK2V617F, a gain-of-function mutant form of tyrosine kinase JAK2, is found in the majority of patients with Ph- myeloproliferative neoplasms (MPNs), a group of chronic hematological diseases that often lead to acute leukemia." (PMID 23210734, 2012). "A fusion of PCM1 and JAK2 is a recurrent abnormality in chronic and acute leukemia." (PMID 25148247, 2014).